ANXA1 (annexin A1)
Diseases named in the same sentence as ANXA1 in open-access papers (continued):
Sharing a sentence is not in itself a finding about the gene and the disease.
lupus nephritis (5 papers, 2018 to 2026). Glomerulonephritis in the context of systemic lupus erythematosus. "In 67% of patients with Lupus nephritis, also Annexin A1 was shown to be modified for the presence of 1 Citrulline in place of Arginine 188 (peptide N178-L198)." (PMID 37176025, 2023). "Anti-Annexin A1 is, in parallel, higher in patients with lupus nephritis compared to both SLE and controls." (PMID 29751523, 2018). "Here, we reviewed the evidence available for an association of anti-Annexin A1 autoantibodies and SLE manifestations, in particular in those cases complicated by lupus nephritis." (PMID 29751523, 2018). "Serum levels of both free Annexin A1 and anti-Annexin A1 antibodies were determined in a relevant cohort of 219 patients, 103 of which presented incipient lupus nephritis at their recruitment." (PMID 29751523, 2018). "Annexin A1 was found to be a main component of NETs, in particular in patients with lupus nephritis who over-expressed this protein." (PMID 29751523, 2018). "New studies also indicate that Annexin A1 in lupus nephritis is a component of NETs that seems of interest in view of the analogy with several other auto-immune conditions, such as small vessel vasculitis, in which components of NETs (i.e., MPO or proteinase 3) serve as antigens for antibodies." (PMID 29751523, 2018). "High circulating levels of anti-ANXA1 and anti-ANXA2 antibodies characterize lupus nephritis implying a reduced anti-inflammatory effect." (PMID 37176025, 2023). "In the unique report on circulating levels, Annexin A1 has been reported to be high in a large cohort of 219 patients with SLE, half of which had Lupus nephritis." (PMID 37176025, 2023). "A first point is that Annexin A1 serum levels are high in patients with SLE and, in particular, in those with lupus nephritis compared to healthy controls matched for age and sex." (PMID 29751523, 2018). "Circulating anti-Annexin A1 antibodies are high, in particular, in SLE complicated by lupus nephritis and/or in cases with cutaneous localization." (PMID 29751523, 2018). "Overall, it seems possible to conclude that the finding of the IgG2 isotype of anti-Annexin A1 antibodies in SLE and lupus nephritis strengthens the general opinion that these two conditions are characterized by antibody specificity." (PMID 29751523, 2018). "We described the presence of circulating auto-antibodies of IgG2 isotype versus Annexin A1 in a high percent of SLE patients and also suggested that these antibodies represent a specific characteristic of lupus nephritis." (PMID 29751523, 2018).
meningitis (5 papers, 2021 to 2024). A disorder characterized by acute inflammation of the meninges of the brain and/or spinal cord. "AnxA1 attenuated inflammatory responses and neutrophil invasion through Fpr2 during S. suis meningitis." (PMID 36776849, 2023). "Although the density of Iba-1-expressing cells was higher in Fpr2−/− mice with meningitis than in WT S. suis-infected mice, AnxA1 reduced microglial activation only in WT mice." (PMID 33318141, 2021). "Together, these data demonstrated that AnxA1 suppresses neutrophil invasion and promotes bacterial removal in the brains of mice with S. suis-induced meningitis through Fpr2." (PMID 33318141, 2021). "AnxA1 attenuates inflammatory responses and brain damage through Fpr2 in mice with S. suis infection meningitis." (PMID 33318141, 2021). "In this study, we used Fpr2−/− mice to estimate the role of murine Fpr2 and exogenous AnxA1 in S. suis-induced meningitis." (PMID 33318141, 2021). "With a particular emphasis on the function of AnxA1 in the regulation of neutrophil recruitment and interleukin-6 (IL-6) production in S. suis-induced meningitis, we demonstrate an immunomodulatory role for AnxA1 in S. suis-induced infection through Fpr2." (PMID 33318141, 2021). "AnxA1 conferred protection against inflammatory responses and neutrophil invasion during S. suis-induced meningitis mainly through Fpr2." (PMID 33318141, 2021). "AnxA1 reduces neutrophil invasion and bacterial loads through Fpr2 in mice with S. suis meningitis." (PMID 33318141, 2021). "However, the specific role of the AnxA1-Fpr2 pathway in S. suis meningitis remains to be determined." (PMID 33318141, 2021). "Another reason for the lower neutrophil counts in the brains of AnxA1-treated WT mice with meningitis might be the induction of phagocytosis by AnxA1 in the periphery." (PMID 33318141, 2021). "In this study, we uncovered that the lack of Fpr2 exacerbated S. suis-induced meningitis in mice infected with the Chinese virulent strain 05ZYH33, and AnxA1 administration exerted anti-inflammatory effects through Fpr2 in S. suis-infected mice." (PMID 33318141, 2021). "Meanwhile, exogenous AnxA1 additionally alleviated inflammatory responses, as characterized by reduced bacterial loads and cytokine levels, migratory astrocyte and microglial responses, and granulocyte invasion, during S. suis meningitis in WT but not Fpr2−/− mice." (PMID 33318141, 2021). "We also found that AnxA1 decreased neutrophil adhesion through Fpr2, and AnxA1 decreased IL-6 expression through the Fpr2/p38/COX-2 pathway, which may clarify the mechanism by which the protein decreased cytokine expression and brain damage during S. suis meningitis." (PMID 33318141, 2021).
metastatic tumors (5 papers, 2018 to 2025). "Remarkably, this independent dataset revealed a significant, progressive downregulation of ANXA1 from distal normal tissues, through premalignant lesions, primary tumors, lymph node metastases, to recurrent/metastatic tumors." (PMID 39896470, 2025). "In particular, ANXA1 expression is expected to be a useful tool to identify which chemotherapy may respond to which patient and when by obtaining tumor samples longitudinally, including metastatic tumors." (PMID 33804148, 2021).
neuroblastoma (5 papers, 2016 to 2023). Neuroblastoma (NB) is the most common solid, extracranial childhood tumor. "Previous studies have shown using plasmid overexpression that annexin A1, A2, A4, A5, and A6 assemble at the plasma membrane of injured neuroblastoma cells in vitro." (PMID 35866481, 2022). "We have reported recently that treatment with recombinant human ANXA1 (hrANXA1) reduced amyloid-β levels by increased degradation in neuroblastoma cells and phagocytosis by microglia." (PMID 34148071, 2021). "Interestingly, our study suggests that incubation of neuroblastoma cells with recombinant ANXA1 lead to an increase in NEP expression and this effect was reversed by FPR2 inhibitors." (PMID 27590054, 2016). "It has been observed that the ionomycin treatment of murine neuroblastoma cells results in translocation to the cell membrane of ANX, in the following order: ANXA2, ANXA4, ANXA6, ANXA1, ANXA5." (PMID 35207075, 2022). "Because ANXA1 is expressed by neurons, we investigated the effect of ANXA1 on APP processing in a neuroblastoma cell line." (PMID 27590054, 2016).
renal cell carcinoma (5 papers, 2014 to 2025). "It was concluded that Annexin A1 is associated with the malignant potential of renal cell carcinoma and, thus, could serve as a marker of poor prognosis." (PMID 34943928, 2021). "More recently, assessment of Annexin A1 expression in renal cell carcinoma of 27 patients was coupled with the use of log-rank test for assessment of disease-free survival." (PMID 34943928, 2021). "ANXA1 has been reported to be highly expressed in epithelial cells of Bowman's capsule, macula densa, and medullary/papillary collecting ducts of the normal rat kidney and overexpressed in multiple human cancers, including conventional renal cell carcinomas." (PMID 24591769, 2014). "RRM2 overexpression plays a key role in sunitinib resistance in patients with renal cell carcinoma and that RRM2 competes with UBE3A to prevent ANXA1 degradation." (PMID 34319001, 2021). "The role of Annexin A1, in conventional renal cell carcinoma (CRCC), without or with metastasis, was investigated with respect to tumorigenesis, metastatic potential and clinical outcome." (PMID 34943928, 2021). "Furthermore, ANXA1 or ANXA2 mRNA or protein levels are altered in various human diseases, for example, cystic fibrosis, hepatocellular carcinoma, prostate carcinoma, pancreatic cancer, breast cancer, and renal cell carcinoma." (PMID 24591769, 2014).
small cell lung carcinoma (5 papers, 2021 to 2025). Small cell lung cancer (SCLC) is a highly aggressive malignant neoplasm, accounting for 10-15% of lung cancer cases, characterized byrapid growth, and early metastasis. "Our aim was to characterize the possible roles of annexin A1 in small cell lung cancer using bioinformatical and cell culture methods." (PMID 40361334, 2025). "ANNEXIN A1 may also be involved in the pathogenesis of bone metastasis in small cell lung cancer (SCLC)." (PMID 34340715, 2021). "In the current study, we investigated ANXA1 expression in 81 squamous cell lung cancer (SQCLC), 86 pulmonary adenocarcinoma (AC), and 30 small cell lung cancer (SCLC) patient-derived tissue samples and its prognostic impact on patient's survival." (PMID 33959206, 2021). "In small cell lung cancer, ANXA1 has not been comprehensively investigated so far, but its upregulation has been identified as a negative, tumor-promoting factor, such as in association with SCLC bone and brain metastases." (PMID 40361334, 2025). "In addition, ANXA1 expression is significantly increased in small cell lung cancer patients with bone metastases than without bone metastases." (PMID 36936694, 2023).
allergic disease (4 papers, 2013 to 2023). An immune response that occurs following re-exposure to an innocuous antigen, and that requires the presence of existing antibodies against that antigen. "Collectively, our findings show that the AnxA1-derived peptide Ac2-26 protects against several pathological changes associated with HDM allergic reaction, suggesting that this peptide or related AnxA1-mimetic Ac2-26 may represent promising therapeutic candidates for the treatment of allergic asthma." (PMID 35269381, 2022). "As studies in animals, especially those related to pharmaceutical products, do not always reproduce the complexity of human allergic diseases, next we tested the effects of exogenous AnxA1 peptide on acute reaction of human MCs." (PMID 34557187, 2021).
B-cell lymphomas (4 papers, 2015 to 2025). "Also, HCL can be distinguished from other B-cell lymphomas, including HCLv, based on annexin A1 expression; indeed, it has been reported that Annexin A1 is a 100% specific immunohistochemical marker for classic HCL." (PMID 39272912, 2024).
bladder tumor (4 papers, 2021 to 2023). "Studies in bladder tumor tissues have shown that ANXA1 had prognostic value in MIBC patients." (PMID 37501157, 2023). "Silencing of ANXA1 inhibits bladder tumor growth using in vitro and in vivo models." (PMID 35784457, 2022). "Functional studies demonstrated that ANXA1 silencing inhibited the proliferation, migration, invasion and epithelial–mesenchymal transition (EMT) of BLCA cells in vitro, and suppressed the growth of xenografted bladder tumors in vivo." (PMID 34991599, 2022).
chronic gastritis (4 papers, 2013 to 2022). Inflammation of the stomach that is chronic in nature. "With respect to the gastrointestinal tract, chronic gastritis displays a high expression of Annexin A1 mRNA that likely contributes to the healing of gastric mucosal damage." (PMID 35563776, 2022).
dengue disease (4 papers, 2022 to 2025). Dengue fever (DF), caused by dengue virus, is an arboviral disease characterized by an initial non-specific febrile illness that can sometimes progress to more severe forms manifesting capillary leakage and hemorrhage (dengue hemorrhagic fever, or DHF) and shock (dengue shock syndrome, or DSS). "We hypothesised that inadequate AnxA1 engagement underlies the cytokine storm and vascular pathologies associated with dengue disease." (PMID 35293862, 2022). "Further investigations should confirm AnxA1 as an underlying mechanism of GCs in dengue disease." (PMID 35293862, 2022). "Our group has previously demonstrated this ability of AnxA1 in studies addressing dengue and chikungunya viruses as well." (PMID 40956847, 2025). "The decline in AnxA1 expression during DENV infection motivated investigation on the role of the AnxA1-FPR2/ALX pathway in dengue disease progression and severity." (PMID 35293862, 2022). "We observed that circulating levels of AnxA1 were reduced in dengue patients and DENV-infected mice." (PMID 35293862, 2022). "Stratification of groups according to disease severity at discharge showed that SD patients had discrete but significantly lower levels of AnxA1 compared to individuals with classic dengue." (PMID 35293862, 2022). "Our results indicate that altered levels of the pro-resolving mediator AnxA1 are of pathological relevance in dengue disease." (PMID 35293862, 2022). "Since we identified reduced levels of AnxA1 in the plasma of dengue patients, we sought to investigate the role of this pro-resolving mediator in dengue’s pathogenesis." (PMID 35293862, 2022). "ANXA1 plays an essential role in balancing inflammation and inhibiting mast cell activation and is a key regulatory factor in cytokine storms and vascular lesions during dengue virus infection." (PMID 40661982, 2025). "Interestingly, we have identified that plasma levels of AnxA1 were reduced in dengue patients compared to healthy controls." (PMID 35293862, 2022). "Levels of AnxA1 were examined in the plasma of dengue patients and infected mice." (PMID 35293862, 2022). "Despite the limitations of modelling dengue disease in immunocompetent animals, infection of AnxA1 KO and FPR2 KO animals (and their respective littermates BALB/c and C57BL/6 mice) with high inoculum of DENV-2 was applied to investigate the role of endogenous AnxA1/FPR2 in dengue disease." (PMID 35293862, 2022). "Given the modulation of AnxA1 expression in DENV-infected mice and the protective role of the AnxA1-FRP2/ALX pathway in experimental disease, we next questioned whether exogenous administration of the AnxA1 mimetic peptide Ac2-26 could attenuate dengue disease." (PMID 35293862, 2022). "We have thereby identified that altered levels of the pro-resolving mediator AnxA1 are of pathological relevance in DENV infection, suggesting FPR2/ALX agonists as a therapeutic target for dengue disease." (PMID 35293862, 2022). "Recently, it has been demonstrated that AnxA1 suppresses excessive inflammation without changing in viral titers during dengue and chikungunya infections in mice." (PMID 40956847, 2025). "The present study confirmed that dengue disease is associated with increased plasma levels of MCPT-1 and identified enhanced secretion in animals lacking AnxA1 or FPR2/ALX." (PMID 35293862, 2022). "Further investigation on GC and GC-inducible AnxA1 is particularly relevant in the context of dengue disease, where the use of non-steroidal anti-inflammatory agents in dengue is discouraged, as they can increase the risk of bleeding." (PMID 35293862, 2022). "In the absence of AnxA1, animals showed more severe and prolonged thrombocytopenia, haemoconcentration, and vascular permeability than WT mice, indicating a protective role of AnxA1 in dengue disease." (PMID 35293862, 2022).
dengue disease (continued). "Taken together, these results reveal the therapeutic potential of a pro-resolving peptide in the context of dengue, supporting the hypothesis that it could be operative also in settings with lower or absent AnxA1." (PMID 35293862, 2022).
dyslipidemia (4 papers, 2019 to 2024). "Deficiency of Annexin A1, in high fat-fed mice, caused more severe abnormalities as revealed by assessment of insulin resistance, dyslipidemia, hepatosteatosis and urinary protein excretion compared to their wild type counterparts." (PMID 34943928, 2021). "Taken together, these findings suggest that ANXA1 protects against the development of dyslipidemia and liver steatosis/injury." (PMID 30972066, 2019). "The role of Annexin A1 has been investigated in microvascular complications of metabolic syndrome." (PMID 34943928, 2021). "WT mice fed on a HFD developed dyslipidemia, had excessive fat accumulation in their peripheral fat beds and in the liver causing hepatic steatosis and liver injury (elevated ALT levels), all of which were more severe in ANXA1−/− mice." (PMID 30972066, 2019).
endometriosis (4 papers, 2013 to 2025). The growth of functional endometrial tissue in anatomic sites outside the uterine body. "The low correlation implies that SomaScan assay and ELISA are measuring different proteoforms of the ANXA1 protein, but regardless they both seem to capture ANXA1 that is positively associated with endometriosis risk." (PMID 40215752, 2025). "Annexin A1 is expressed in the endometrium and is specifically present in women with endometriosis, although the available studies are still inconsistent." (PMID 33922064, 2021). "Interestingly, while ANXA1 values measured in SomaScan did not correlate with ANXA1 values measured in ELISA, we did observe similar direction of association with endometriosis risk." (PMID 40215752, 2025).
gestational diabetes (4 papers, 2018 to 2024). Carbohydrate intolerance first diagnosed during pregnancy. "Studies have shown an association between ANXA1 levels and the development of pregnancy-associated diseases such as pre-eclampsia (PE) and gestational diabetes mellitus (GDM)." (PMID 35805141, 2022). "Certainly, ANXA1 expression is increased in the placenta at term of normal pregnancies whereas lower levels of ANXA1 are present in the placentas from Gestational Diabetes Mellitus pregnancies that have a high level of inflammatory cytokines." (PMID 29614751, 2018). "Placenta was collected from ANXA1 knockout mice (AnxA1−/−) and pregnant women with gestational diabetes mellitus (GDM)." (PMID 37373303, 2023).
glaucoma (4 papers, 2018 to 2025). Increased pressure in the eyeball due to obstruction of the outflow of aqueous humor. "ANXA1 is associated with various eye diseases, including glaucoma and retinopathy due to hypoxia and ischaemia." (PMID 41488750, 2025). "Our previous study found that nuclear translocation of ANXA1 is associated with glaucoma-induced apoptosis of RGCs." (PMID 30364320, 2018). "However, in mouse models of glaucoma, it is still unclear whether ABCA1 participates in ANXA1 membrane translocation, and whether and how blocking TBK1 directly protects against RGC apoptosis." (PMID 30364320, 2018).
oral cancer (4 papers, 2013 to 2022). "Recently, Lin and colleagues analyzed 115 patients with oral carcinoma and observed high expression of ANXA1 in the nucleus of epithelial tumor cells that correlated with poor prognosis." (PMID 25490767, 2014).
osteoarthritis (4 papers, 2023 to 2026). A noninflammatory degenerative joint disease occurring chiefly in older persons, characterized by degeneration of the articular cartilage, hypertrophy of bone at the margins and changes in the synovial membrane. "PPARγ controls ESCRT-dependent FLSs exosome biogenesis and alleviates chondrocyte osteoarthritis mediated by exosomal cargo ANXA1 protein." (PMID 40678612, 2025). "Regarding whether Anxa1 exerts joint‐protective effects through TGFβ regulation, some studies have indicated that EVs derived from neutrophils of Anxa1‐deficient mice can inhibit the expression of cartilage degradation factors induced by IL‐1β stimulation in osteoarthritis without relying on Anxa1." (PMID 40125663, 2025).